INS (insulin)
Diseases named in the same sentence as INS in open-access papers (continued):
Sharing a sentence is not in itself a finding about the gene and the disease.
overnutrition (continued). "The notion that overnutrition—i.e., consumption of too much food per meal and/or too many meals—might represent a chronic ER stress was first suggested in 2004, in seminal work demonstrating that ER stress was observed in the livers of obese mice, and was tied to hepatic insulin resistance." (PMID 27938665, 2016). "Prolonged starvation, overnutrition, and glucagon all upregulated FGF21 expression, while insulin may inhibit FGF21 expression in the liver." (PMID 39296716, 2024). "Hereby, undernutrition has a negative impact, and overnutrition has a positive impact on these processes, possibly via insulin, leptin, or thyroid hormones." (PMID 39684351, 2024). "In both cases, early overnutrition produced a decrease in the activation of the PI3K-Akt pathway in myocardial tissue, which, in the rat model, was also translated in decreased heart contractility in response to insulin." (PMID 37833890, 2023). "Specifically, the PM sn-1,2-DAG/PKCε/Insr Thr1160 pathway that is responsible for lipid-induced hepatic insulin resistance, which occurs in MAFLD, may also account for lipid-induced WAT insulin resistance in the early stages of overnutrition." (PMID 33411692, 2021). "To investigate the effects of early overnutrition on β cell mass in adults, we examined insulin stained pancreas sections in non-diabetic males." (PMID 30842440, 2019). "The NSAPP pathway fails to function normally in states of overnutrition, thereby providing a molecular explanation for pathway-selective insulin resistance, also known as imbalanced insulin action." (PMID 29632515, 2018). "There were no persistent effects of exposure to maternal overnutrition during pregnancy and lactation on plasma glucose, insulin or cholesterol levels or HOMA-IR in either sex." (PMID 25082159, 2014). "Moreover, since both overnutrition and alcohol activate RAS, and alcohol dampens insulin-signaling, insulin resistance is further exacerbated in cardiac tissue." (PMID 21977024, 2012). "However, chronic overnutrition accompanied with neuroinflammation, BBB disruption, and brain insulin resistance could halt OPCs and oligodendrocytes, leading to hypomyelination." (PMID 39684351, 2024). "Lifestyle factors such as overnutrition, physical inactivity, and psychosocials coupled with systemic low-grade inflammation have a strong negative impact on glucose homeostasis, in particular, insulin sensitivity." (PMID 38212326, 2024). "Overnutrition and overweight can increase DAG content in the liver due to high delivery of free fatty acids from the circulation or due to increased de novo lipogenesis, which both increase intrahepatocellular lipid content, leading to liver insulin resistance." (PMID 38989003, 2024). "However, the effects of early overnutrition on cardiovascular insulin sensitivity in the long-term had not been explored yet." (PMID 37833890, 2023). "During overnutrition, toxic metabolites including ceramides, diacylglycerol (DAG), and nonesterified fatty acids (NEFA) accumulate and stimulate the activity of protein kinase C (PKC), leading to the Ser/Thr phosphorylation of IR and IRS, thereby impairing insulin sensitivity." (PMID 37960324, 2023). "In overnutrition status, the excess intra-cellular free fatty acids will lead to the activation of PKC and NFκB, then induce serine 307 phosphorylation for IRS-1, which inhibits the insulin signal pathway and eventually results in IR in the skeleton muscle and hepatocytes." (PMID 33019649, 2020). "Taken together, these data suggest that maternal hyperleptinemia programs the vascular endothelium in mesenteric resistance vessels not to respond to overnutrition with an enhanced capacity for eNOS-dependent vasodilation and to reduce its responsiveness to insulin." (PMID 27187080, 2016). "More studies are needed to determine when these early responses can no longer sustain normal whole-body insulin sensitivity and which individuals may not be as capable of adapting to overnutrition and why." (PMID 19781106, 2009).
overnutrition (continued). "Furthermore, chronic overnutrition activates several lipogenic factors independent of the insulin signaling pathway, such as the substrate-driven redistribution of circulating fatty acids caused by IR in adipose tissue, which contributes a significant amount of triglycerides." (PMID 41155548, 2025).
acne (116 papers, 2010 to 2026). An inflammatory process of the sebaceous glands which is characterized by comedones, nodules, papules and/or pustules on the skin. "Increased blood glucose levels were linked to acne patients mostly because they cause insulin to be secreted, which reduces the binding protein for IGF-1 and encourages IGF-1 cell proliferation." (PMID 38255795, 2024). "The reports of insulin resistance in patients with severe acne and the association of acne with diets delivering high glycaemic loads create a strong basis to examine the role of insulin in SG function." (PMID 37727660, 2023). "On the other hand, the association between insulin resistance biomarkers and severity of acne vulgaris clarified significant differences for both C-peptide and TyG index (P < 0.01)." (PMID 36852374, 2023). "Raised blood glucose values are associated with acne patients principally because an increase in blood glucose levels triggers insulin secretion, which decreases the binding protein for IGF-1, promoting cell proliferation by IGF-1." (PMID 35677010, 2022). "Higher fasting and postprandial insulin values can cause acne flare-ups by increasing basal keratinocyte proliferation." (PMID 35677010, 2022). "The recent viewpoint on the pathogenesis of acne underlines that a western diet (WD) characterized by hyperglycemic carbohydrates and dairy protein consumption increases the insulin/IGF-1 signaling, thereby promoting acne." (PMID 34418600, 2021). "Elevated IGF-1 and insulin that is mediated by western diet increases sebaceous gland growth and sebaceous lipogenesis, which causes hyper- and dysseborrhea in acne patients." (PMID 31951642, 2020). "Western diet and puberty, which are the two main risk factors of acne vulgaris, increase insulin/IGF-1 signaling and activate Akt." (PMID 31824416, 2019). "The occurrence of acne as part of various syndromes associated with insulin resistance further supports the association between insulin and acne." (PMID 28513546, 2017). "A low-glycemic load diet, one rich in plant fibers and low in processed foods, has been linked to an improvement in acne, possibly through gut changes or attenuation of insulin levels." (PMID 28513546, 2017). "The intake of oily fish reduces the risk of acne by lowering fasting insulin levels." (PMID 38873457, 2024). "In contrast, lysozyme cannot kill C. acnes, which may explain its minor upregulation in acne skin biopsies.The expression of AMPs can also be affected by several AV-associated factors, such as FFAs, glucose, insulin, or IGF-1 levels." (PMID 39744637, 2024). "On the other hand, consumption of dairy milk products has been associated with a higher frequency and severity of acne, as its components enhance the effects of insulin and IGF-1 on the production of androgen hormones and sebum and stimulate the formation of comedones." (PMID 37727660, 2023). "However, certain skin conditions, such as acrochordon and acne, have been linked with insulin action." (PMID 34203830, 2021). "Therefore, AMPs could be key determinants in regulating AV development and progression, linking acne-associated immune responses and metabolic factors, like insulin/IGF-1 and PI3K/Akt/mTOR/FoxO1 signaling pathways or glucotoxicity." (PMID 39744637, 2024). "Therefore, AMPs may be key determinants in developing and progressing acne-associated immune responses, skin barrier integrity, and metabolic factors, like insulin/IGF-1 and PI3K/Akt/mTOR/FoxO1 signaling pathways or high glucose levels." (PMID 39744637, 2024). "As a result, insulin and carbohydrate metabolism may play a role in the cause and severity of acne." (PMID 36852374, 2023). "Thus, there is compelling translational evidence that increased insulin/IGF-I signaling in acne with deficient nuclear availability of FoxO transcription factors may enhance survivin expression." (PMID 27803511, 2016).
acne (continued). "Otherwise, a diet that reduces the glycaemic load results in insulin sensitivity improvement and in the reduction in sapienic acid, which is correlated with a decrease in acne severity." (PMID 40422250, 2025). "Together, these data provide compelling evidence that targeting insulin resistance with metformin is a mechanistically justified and clinically effective adjunct strategy in acne management." (PMID 40868844, 2025). "Pharmacological therapies targeting both acne and metabolic dysfunctions, such as metformin, have shown promise in improving insulin sensitivity and reducing inflammatory markers." (PMID 40358870, 2025). "A significant difference between the two groups (P = 0.001) was found, indicating that the combination of rapid insulin and microneedling offers a therapeutic advantage for treating atrophic scars due to acne vulgaris compared with microneedling alone." (PMID 40755873, 2025). "IGF- 1 promotes sebaceous gland proliferation and sebum production in acne, while simultaneously influencing lipid metabolism and insulin sensitivity." (PMID 40358870, 2025). "In hyperandrogenic women, elevated insulin levels, due to impaired insulin function, enhance ovarian androgen production, disrupting the menstrual cycle and promoting features such as hirsutism, acne, and alopecia." (PMID 40964529, 2025). "Skin needling with insulin has been shown to improve acne scars and stria alba (stretchmarks), and some of the authors have replicated these results by reducing facial rhytids." (PMID 40585019, 2025). "This prospective study evaluated the efficacy and safety of microneedling combined with topical insulin for treating various atrophic scars, including those from acne and cutaneous leishmaniasis." (PMID 40755873, 2025). "The insulin/IGF-1 pathway over-stimulation in acne patients results in the hyper-stimulation of DNL and thus in excessive and deregulated sebum production." (PMID 40422250, 2025). "One trial focused on PCOS and found superiority of simvastatin in effects on lipids, CRP, and acne; metformin performed better in terms of effects on blood sugar and insulin measures." (PMID 40808694, 2025). "Increased basal keratinocyte proliferation can lead to acne flare-ups when fasting and postprandial insulin levels are high." (PMID 38255795, 2024). "As regards the prevalence of dermatological manifestation reported in the present study as well as its relation to waist circumference as an indicator of insulin resistance, acne was the most common dermatological manifestation in the current study." (PMID 38883100, 2024). "Randomized controlled trials support this, indicating that a 10-week low glycemic load diet and probiotics improve acne, enhancing insulin sensitivity and reducing androgen-related factors." (PMID 38562266, 2024). "A primary manifestation of acne pathology is the development of comedones, often linked to the overproduction of sebum resulting from 5α‐dihydrotestosterone (5α‐DHT) and insulin activity." (PMID 39087744, 2024). "Studies have revealed that various hormones, including androgens, estrogen, insulin, insulin-like growth factors, and others, play a pivotal role in the pathogenesis of acne, with androgens being the most significant endogenous contributor." (PMID 39050538, 2024). "in 2014 in Turkey, titled “Insulin Sensitivity, Androgens, and Isotretinoin Treatment in Women with Severe Acne,” the levels of insulin and androgen sensitivity before and after treatment with isotretinoin were examined." (PMID 39143842, 2024). "The variables in this study included androgen levels, lipids, glucose, and insulin levels, which were evaluated in 26 patients with severe acne and 21 healthy individuals during insulin resistance testing." (PMID 39143842, 2024). "In the MPG, most severe acne patients were overweight (52.1%), insulin-resistant (48.8%), or obese (47.9%)." (PMID 38541239, 2024).
acne (continued). "The mechanisms by which an anti-inflammatory diet affects acne include the regulation of insulin and IGF-1 levels, which are involved in sebum production and inflammatory processes." (PMID 38998499, 2024). "Oily fish intake was found to be a protective factor for acne (OR: 0.22, 95% CI: 0.10-0.49, p < .001), and it was also observed that oily fish intake can reduce the level of fasting insulin by the IVW method (OR: 0.89, 95% CI: 0.81-0.98, p = .02)." (PMID 38873457, 2024). "Recently, there have been reports on the possible influence of excess insulin on androgen metabolism in the adrenal glands and gonads primarily during adolescence; this can exacerbate acne lesions." (PMID 36986218, 2023). "There has been no case‐control study investigating the relationship between acne and MetS despite numerous studies related to insulin resistance." (PMID 37752973, 2023). "It has also been demonstrated that a low-glycemic index diet improves acne severity as well as insulin sensitivity in young males with acne vulgaris." (PMID 36852374, 2023). "Elevated serum glucose and insulin levels correlated with sebum overproduction and the severity of acne lesions." (PMID 36986218, 2023). "Affecting the metabolic processes in the SG, insulin is a major hormonal trigger in acne development." (PMID 37727660, 2023). "In the articles reviewed in this paper, insulin resistance was found to be more frequent in acne vulgaris patients." (PMID 37626790, 2023). "Due to the implication of a high glycemic diet and insulin/IGF-1 in the pathogenesis of acne, mechanisms of abatement of insulin level or action are useful targets in the treatment of this disorder." (PMID 37727660, 2023). "A low-glycaemic diet results in an improvement of insulin sensitivity and acne severity associated also with an improvement in the fatty acid composition of sebum." (PMID 37727660, 2023). "In this review, we examined the effects of insulin on the SG function and their implications in the pathogenesis of acne." (PMID 37727660, 2023). "Poorly differentiated sebocytes exhibited decreased expression of PPAR and elevated levels of IGF-1 receptors and insulin, leading to the generation of sebum and mediators of inflammation resembling acne." (PMID 37687224, 2023). "We also observed that hirsutism, acne, alopecia, insulin, and testosterone were higher in women with PCOS who had MS." (PMID 35642189, 2022). "Elevated insulin levels in adolescence lead to increased serum androgen levels and stimulate sebum and keratinocytes in the skin, leading to the development of acne lesions." (PMID 36161627, 2022). "BMI, severity of hirsutism, finding or severity of adult acne or female pattern hair loss, LH/FSH ratio, estradiol, AMH and insulin were similar in the two subgroups of PCOS women." (PMID 36291122, 2022). "In contrast to the control group, the patients with resistant acne disease had a higher BMI, blood insulin and glucose concentrations and lower HDL cholesterol." (PMID 36678524, 2022). "Cellular mechanisms governing acne pathogenesis include insulin-stimulated activation of the PI3K-Akt signaling pathways along with mTOR in sebocytes, resulting in increased synthesis of proteins and lipids, cell proliferation, and inflammation." (PMID 36614827, 2022). "A previous study reported elevated IGF-1 levels in cases of acne, potentially indicating a possible influence of insulin and growth hormone levels." (PMID 35677010, 2022). "Age, BMI, waist circumference, free testosterone, 2-hr insulin levels, acne, acanthosis, and hirsutism were significantly higher in women with PCOS who had MS compared to those without MS." (PMID 35642189, 2022). "Classically, acne has been associated with an increase in androgens at the systemic and local levels, but the influence of IGF-1 and insulin, which in turn are dependent on diet, is transcendental." (PMID 35889022, 2022).